SIAH2 (siah E3 ubiquitin protein ligase 2)
Diseases named in the same sentence as SIAH2 in open-access papers (continued):
Sharing a sentence is not in itself a finding about the gene and the disease.
SIAH2 also shares sentences with these, for which no sentence is quoted: glioma (2 papers); lung squamous cell carcinoma (2); non-small cell lung carcinoma (2); B-cell acute lymphoblastic leukemia (1); colon adenocarcinoma (1); dyskeratosis congenita (1); esophageal squamous cell carcinoma (1); Glucose intolerance (1); hematologic malignancies (1); hepatocellular carcinoma (1); osteosarcoma (1); ovarian cancer (1); prostate tumors (1); rectal cancer (1); squamous non-small-cell lung carcinoma (1); stomach cancer (1); ulcer (1).